MMP9 (matrix metallopeptidase 9)
Diseases named in the same sentence as MMP9 in open-access papers (continued):
Sharing a sentence is not in itself a finding about the gene and the disease.
breast carcinoma (continued). "In this study, we investigated depressive effect on MTA1 by MTA1-specific short hairpin RNA(shRNA) expression plasmids in human breast cancer cell lines MDA-MB-231 and MCF-7, and effect on protein levels of ER alpha, MMP-9, cyclinD1, and tumor cell invasion, proliferation." (PMID 21595884, 2011). "Transfection of CD147 cDNA into human MDA-MB436 breast cancer cells resulted in an enhancement of tumor growth and an increase in metastatic incidences, both of which were directly correlated with high levels of tumor-derived MMP-2 and MMP-9." (PMID 20525232, 2010). "To investigate whether melatonin regulates breast cancer cell invasion by altering the expression of MMPs, particularly MMP-2 and MMP-9, we examined the effect of melatonin on MMP-2 and MMP-9 protein expression in the conditioned medium using MCF-7/6 cells." (PMID 21167057, 2010). "Our findings have showed that BER suppresses the growth, migration and invasion in highly-metastatic human breast cancer cells by possibly inhibiting Akt and NF-κB signaling with their upstream target c-Met and downstream targets Bcl-2/Bax, osteopontin, VEGF, MMP-9 and MMP-2." (PMID 19796390, 2009). "We analyzed the expression levels of MMP-2, MMP-9 and MMP-14 and their inhibitors (TIMP-1, TIMP-2 and RECK) by quantitative RT-PCR (qRT-PCR) in five human breast cancer cell lines presenting increased invasiveness and metastatic potential, 72 primary breast tumors and 30 adjacent normal tissues." (PMID 19144199, 2009). "Here, we propose a more comprehensive approach by analyzing the expression levels of several MMPs (MMP-2, MMP-9 and MMP-14) and MMP inhibitors (TIMP-1, TIMP-2 and RECK) in different models (five human breast cancer cell lines, 72 primary breast tumors and 30 adjacent normal tissues)." (PMID 19144199, 2009). "Here, we proposed a more extensive approach by analyzing the mRNA expression levels of different MMPs (MMP-2, MMP-9 and MMP-14) and MMP inhibitors by qRT-PCR (TIMP-1, TIMP-2 and RECK) in several models (five human breast cancer cell lines, 72 primary breast tumors and 30 adjacent normal tissues)." (PMID 19144199, 2009). "The best features to detect breast cancer were MIF, MMP-9, and MPO." (PMID 19476629, 2009). "And, the MMP-9/lipocalin 2 complexes were detected in 90% of urine samples obtained from breast cancer patients, but not in those from healthy controls." (PMID 19077278, 2008). "Likewise, it has been recently reported that MMP-7 overexpression in breast cancer (MCF-7) cells enhances cellular invasiveness and activation of proMMP-2 and MMP-9." (PMID 17342087, 2007). "However, slightly lower levels of TGFβ1 (P<0.0001) and MMP-2 (P=0.03) and a small increase of MMP-9 (P=0.001), OPG (P=0.003) and CTX (P=0.0007) have been detected in breast carcinoma patients." (PMID 16880790, 2006). "Western blot analysis confirmed this absence of MMP-7 and, furthermore, the basal level MMP-9 and uPA produced by the monocyte cells was not changed upon exposure to the breast cancer CM (results not shown)." (PMID 16168111, 2005). "A study of a breast cancer cell lines stimulated with EGF showed an increase in MMP9 but not MMP2, but this increase was not inhibited by the tyrosine kinase inhibitor PD153035." (PMID 15083203, 2004). "For example, transfection of MCF-10A breast cancer cells with either c-erbB-2 or c-ras resulted in increased expression of MMP-2, whereas transfection of MCF-7 cells with the ets gene PEA-3 led to increased production of MMP-9." (PMID 15054465, 2004). "Our qualitative analysis of the zymograms showed that the majority of the 80 sera samples from breast cancer patients displayed sharp bands of lysis corresponding to the proenzyme forms of MMP-2 and MMP-9, respectively, in contrast to the 22 control samples which showed less pronounced lytic bands." (PMID 15054465, 2004).
breast carcinoma (continued). "Furthermore, WISP1 appears to act as a regulator of extracellular matrix remodeling in breast cancer, broadly enhancing the expression of matrix metalloproteinases, including MMP1, MMP2, MMP9, and MT1-MMP, and shifting the MMP/TIMP balance toward a proteolytic phenotype." (PMID 41597235, 2026). "Similarly, CXCL13/CXCR5 signaling can upregulate MMP-9 through the RANKL-Src axis, which other studies showed could facilitate lymph node metastasis in breast cancer." (PMID 40295829, 2025). "Moreover, MMP-9, an important oncogene, belongs to the zinc-dependent endopeptidase family, can degrade ECM, and plays a vital role in tumorigenesis and metastasis, such as breast cancer, acute leukemia, pancreatic cancer, and even lung cancer." (PMID 40034591, 2025). "Furthermore, ATF6 has been shown to promote brain metastasis in breast cancer while XBP1 supports invasion and proliferation by inducing MMP9 (matrix metalloproteinase-9) expression and remodelling of the extracellular matrix in human esophageal squamous cell carcinoma." (PMID 41228282, 2025). "In addition, the LCN2/MMP9 complex is present in the urine of 86.36% of patients with breast cancer but is not detected in healthy donors." (PMID 40109857, 2025). "Previous studies have shown that MCF-7 breast cancer cells, which naturally produce MMP-9, stably transfected to express LCN2, form tumors in xenograft models characterized by enhanced tumor growth, proliferation, and microvessel density compared to wild-type MCF-7 tumors expressing MMP-9 only." (PMID 40732340, 2025). "Additionally, it could reduce the invasion and metastasis of MDA-MB-231 breast cancer cells by suppressing the expression of matrix metallopeptidase 2 (MMP-2) and matrix metallopeptidase 9 (MMP-9)." (PMID 38505423, 2024). "ABI1 also localizes to invadopodia in MDA-MB-231 breast cancer cell lines, and ABI1 knockdown impairs invadopodia formation, inhibits tumor cell proliferation and migration, decreases SRC activation, and downregulates matrix metalloproteinase 9 (MMP9) expression." (PMID 39354505, 2024). "Furthermore, MG-BSA-AGEs increase the expression of RAGE and ERK1/2 phosphorylation in different breast cancer cell lines, alongside increased expression of ER-α and ER-β without active forms of MMP-9/MMP-2 in ER positive cell lines." (PMID 39830522, 2024). "Associated with poor prognosis; MTs promote the proliferation of breast cancer cells by promoting the cell cycle, regulating oxidative stress, inhibiting apoptosis, increasing DOX resistance of breast cancer, and enhancing the aggressiveness by upregulating MMP‐9 via AP‐1 and NF‐κB activation." (PMID 39676279, 2024). "Moreover, the expression of inflammatory markers, including granulocyte-colony-stimulating factor (G-CSF) and matrix metalloproteinase-9 (MMP-9), was higher in serum samples from antibiotic-treated and untreated bone metastatic breast cancer mice compared to control mice." (PMID 39596154, 2024). "In breast cancer, platelets MPs can promote adhesion of mammary cancer cells to human umbilical vascular endothelial cells (HUVEC), through the transfer of CD41, and also induce chemotaxis, invasion and upregulate the production of matrix metalloproteases (MMP) such as MMP-2 and MMP-9." (PMID 39510381, 2024). "In addition, several MMPs that contribute to the proteolysis of collagen-425,26, including MMP2, MMP3, MMP9, and MMP14, were upregulated in either lung fibroblasts exposed to breast cancer cell-conditioned media, or premetastatic lungs in metastatic primary tumor-bearing mice." (PMID 37903851, 2023). "Notably, MMP9 had a staggering amplification frequency of 40.4% in colorectal cancer and 33.7% in esophagogastric cancer, while PTGS2 had an amplification rate of 34.1% in breast cancer." (PMID 37033970, 2023).
breast carcinoma (continued). "While the types of breast cancer were not delineated in the study, an association between dysregulated PADI3, upregulated MMP9, triple-negative inflammatory breast cancer (TNIBC), and triple-negative non-inflammatory breast cancer (TN-NIBC) has been documented in the literature." (PMID 37109551, 2023). "Recently bLF was reported to inhibit the invasion of breast cancer cells via the inhibition of FAK phosphorylation at tyrosine (Tyr)-397, and enhanced AMP-activated protein kinase activity (AMPK) thereby inhibited the expression of MMP-2 (Gelatinase A) and MMP-9 (Gelatinase B)." (PMID 36839884, 2023). "Interestingly, the MMP-9 luciferase reporter gene and chromatin immunoprecipitation (ChIP) assays carried out on breast cancer MDA-MB-231 cells under hypoxic conditions, showed that HIF-1 forms a complex with p300 that increases MMP-9 promoter activity, including H3 and H4 acetylation." (PMID 38069210, 2023). "Studies to establish MMP-9 expression, downstream of FAK protein activation and β-catenin stabilization (by performing FAK knockout and luciferase promoter reporter chromatin immunoprecipitation assays) in breast cancer cells, would also elucidate these relationships." (PMID 38068928, 2023). "In addition, plasma MMP-2 and MMP-9 were significantly reduced in breast cancer patients after surgery, so both MMP-2 and MMP-9 could be used as markers of breast cancer disease response to therapy." (PMID 37496657, 2023). "Thus, we hypothesized that under conditions mimicking obesity, an increase in β-catenin accumulation and MMP-9 protein expression would occur downstream of FAK activation, leading to a subsequent increase in breast cancer cell migration and invasion." (PMID 38068928, 2023). "It was observed that NOTCH-1 activation is responsible for inducing the MMP-2 and MMP-9 expression and stimulation while lowering the regulation of NOTCH-1 involved in lowering the MMP-2 and MMP-9 activation to hinder cell progression in breast cancer and pancreatic cancer cells." (PMID 36359888, 2022). "Moreover, the downregulation of MMP-9 followed by the cytostatic treatment reduced migration and invasion (wound healing assay, chemotaxis test) and influenced the level of EMT markers in cells of both breast cancer cell lines." (PMID 34884588, 2021). "Furthermore, ST3Gal-III modulated breast cancer cell adhesion and invasion by altering sLex expression, E-selectin binding capacity, and invasion-related protein expression including β1 integrin, MMP-2, and MMP-9." (PMID 34577144, 2021). "Taken together, our data indicate that BAALC directly interacts with FAK, and that BAALC overexpression led to an increase in the expression of active MMP-9 suggesting that BAALC may enhance breast cancer cell migration and invasion through a FAK and MMP-9-mediated mechanism." (PMID 33968759, 2021). "It is revealed that FZYLF significantly inhibits the invasion and metastasis of the multidrug-resistant breast cancer cells MDA-MB-231/Adr and the mechanism of action may be related to its inhibition of the abnormal protein expression of WAVE3 gene, MMP-9, p-IκBα, and NF-κB (p65)." (PMID 33854560, 2021). "Therefore, ORM1 may represent a potential therapeutic target for breast cancer and promote epirubicin resistance by regulating the expression of MMP-2 and MMP-9, as well as activating the AKT/ERK signaling pathway." (PMID 34654351, 2021). "Our study reveals a new molecular regulatory mechanism, that is, TIMELESS can inhibit breast cancer migration and invasion by reducing the transcription activity of MMP9, and systematically expounds the molecular mechanism of TIMELESS regulating NF-κB/MMP9 pathway." (PMID 33430865, 2021). "Moreover, we found that enriched autophagy-associated GPR64 in hypoxic CAFs-derived exosomes upregulates MMP9 and IL-8 in recipient breast cancer cells via non-canonical NF-κB signaling, which is required for breast cancer cells to gain invasive abilities." (PMID 34830956, 2021).
breast carcinoma (continued). "Concerning the inhibition of the tumorigenesis and metastasis of breast cancer, ISL can rectify the abnormal PI3K/AKT, NF-kB, and p38 signaling pathways in order to reduce the occurrence of metastasis through correcting the expression of MMP-2, MMP-7, MMP-9, VEGF, and HIF-1α." (PMID 33401375, 2021). "In breast cancer cell lines, MCF-7 and MDA-MB-436, 5-aza-2′-deoxycytidine induced the demethylation of CpG sites in the MMP9 promoter and histone H3 lysine-4-trimethylation (an epigenetic marker of open chromatin-allowing gene transcription), resulting in increased MMP9 expression." (PMID 33920915, 2021). "They found that exosomes isolated from macrophages after coculture with apoptotic breast cancer cells demonstrated the ability to induce proliferation, invasiveness, and metastasis of breast cancer in vitro and in vivo by activating STAT3 and its target genes CyclinD1, MMP2, and MMP9." (PMID 34207035, 2021). "The results showed that MMP9, MMP12, MMP15, and MMP27 groups were all highly variable (p < 0.01), whereas the other groups were not markedly different, indicating that these genes may play important roles in the occurrence and development of breast cancer." (PMID 35069702, 2021). "To assess whether DANCR regulates EMT or cancer stemness of malignant breast cancer cells, we first examined the expressions of EMT‐related biomarkers, including SNAIL1, SLUG, MMP‐2, MMP‐9, E‐cadherin, and Vimentin in shDANCR vs. shNC (MDA‐MB‐231 and MDA‐MB‐468) cells." (PMID 31860165, 2020). "Similarly, the exogenous CXCL1 could partly restore MMP2 and MMP9 levels that were suppressed by XIAOPI formula, suggesting that XIAOPI might inhibit the invasion of breast cancer cells in a CXCL1 dependent manner." (PMID 32213179, 2020). "MMP-9 was shown to be upregulated in the basal-like triple negative and HER2 positive breast cancer cell lines, and MMP-9 knockdown was shown to block metastasis in both triple negative breast cancer cell models and an orthotopic mouse model of human breast cancer." (PMID 32466129, 2020). "Breast cancer cell-derived supernatant treated neutrophils significantly expressed high levels of interleukin-1β (IL-1β), CC-chemokine ligand-2-4 (CCL2, CCL3, CCL4), inducible nitric oxide synthase (iNOS), and matrix metallopeptidase-9 (MMP9), and formed extracellular traps (NETs)." (PMID 33049964, 2020). "Furthermore, arctigenin intervention suppressed protein expressions and mRNA level of GM-CSF, MMP-3, MMP-9 and TSLP in breast cancer cells, suggesting that arctigenin decreases the secreted GM-CSF, MMP-3, MMP-9 and TSLP at the transcriptional level in breast cancer cells." (PMID 32887217, 2020). "However, effective therapies targeting MMP9 have failed to extend survival for patients with breast cancer and other tumors." (PMID 33119681, 2020). "Metformin was proved to reduce MMP9 synthesis in many different pathologies e.g., in adipocytes in insulin resistant diabetes, in breast cancer, in spinal cord injury, etc., but so far no scientific article demonstrated this effect in eye of diabetic animals as in this present study." (PMID 32204537, 2020). "In addition, IL-8 and other pro-inflammatory cytokines also cooperate with TGF-β1 in the production of matrix metalloproteinase-9 (MMP-9) by breast cancer cells, and TGF-β-activated protein kinase 1 is required for this response, contributing to the metastatic potential of breast cancer cells." (PMID 31847214, 2019). "In addition, FAM53A may affect the migration and invasion of breast cancer cells by regulating the expression of RhoA, RhoB, RhoC, ROCK1, and MMP9." (PMID 31799197, 2019). "Moreover, in breast cancer MCF-7 and MDA-MB-231 cells, quercetin treatment inhibited epithelial-mesenchymal transition determined by expression of markers such as vimentin, Snail, N-cadherin, Twist, Slug, MMP2, and MMP9, by suppressing EGFR/VEGFR2 signaling." (PMID 31100782, 2019).
breast carcinoma (continued). "A drop in MMP-2 and MMP-9 activity was detected in addition to its effects on other several apoptotic pathways after quercetin treatment in multiple cancer cell lines i.e., human head and neck squamous cell carcinoma (HNSCC), colon cancer (Caco-2 cells), and breast cancer (MCF-7 cells)." (PMID 31064104, 2019). "In addition to MMP9, BMAL1 also up-regulated the downstream target genes of NF-κB in breast cancer cells, such as TNF, IL8, uPA, and luciferase reporter gene showed that BMAL1 could activate the activity of NF-κB reporter gene." (PMID 31346317, 2019). "Similarly, the effect of phytochemicals on MMP-2, MMP-9, and their tissue inhibitors (TIMPs) has been tested in breast cancer, with no alterations observed in vitro." (PMID 31921634, 2019). "Recent studies in breast cancer cells have revealed that CXCR7 activation by SDF‐1 increases components regulating cell adhesion and cell–matrix interaction, such as vascular adhesion molecule VCAM‐1 and matrix metalloproteinases MMP‐2 and MMP‐9, and SDF‐1 also promoted MMP‐9 expression in OC cells." (PMID 30051594, 2018). "The finding that TNF-α could induce fusion via an MMP9-dependent mechanism is further supported by data showing that the fusion of osteoclasts in bone explants, which were stimulated by human breast cancer cells through TNF-α secretion, could be blocked by the inhibition of MMP9." (PMID 29636110, 2018). "Although previous studies have suggested a close association of MMP-9 with triple negativity of breast cancer, metastasis, and the poor prognosis of TNBC5,6, the current study demonstrated that similar to CTSS, the suppression of MMP-9 alone was not enough to block the TNBC invasion." (PMID 30185799, 2018). "Studies have also reported that decursin inhibits matrix metallopeptidase 9 (MMP-9)-induced cytoskeletal rearrangement by suppressing phosphoinositide 3-kinase (PI3K), extracellular signal-regulated kinase (ERK), and NFκB activation in fibrosarcoma and breast cancer cell lines." (PMID 30060484, 2018). "Furthermore, this study is the first report to suggest the molecular targets involved in the BHMC mechanism for controlling the invasiveness of MDA-MB-231 human breast cancer cells, whereby treatment of BHMC at 12.5 μM reduced the expression level of β-PIX, MMP-9, and MT1-MMP." (PMID 29642589, 2018). "Interestingly, LIPUS treatment in co-culture system, which is closer to an in vivo setting, seemed to have a greater inhibitory effect on the osteolytic capacity of metastatic breast cancer cells, in particular for Trap and Ctsk expression and CTSK and MMP9 protein release." (PMID 30126457, 2018). "Additionally, surgical resection may promote tumor growth and metastasis through increased matrix metalloproteinase 9 (MMP-9) and VEGF expression, as in one model of breast cancer." (PMID 29347949, 2018). "This is the first work to reveal that casticin treatment inhibited breast cancer cell migration and invasion through down-regulation of the PI3K/Akt signaling pathway and blockage of c-Jun and c-Fos nuclear translocation, which finally resulted in a decrease in MMP-9 expression." (PMID 30401729, 2018). "LIPUS treatment was able to decrease the capability of breast cancer cell culture medium to induce osteoclastic differentiation in Raw264.7, showing a significant reduction of multinucleate TRAP+ cells,as well as CTSK and MMP9 expression and release, using both direct and indirect approaches." (PMID 30126457, 2018). "The data in the present study suggest that MMP-9 may not be a major contributor to breast cancer progression/inhibition in human breast tissue in vivo." (PMID 29387062, 2017). "Furthermore, I3C could induce inhibition on breast cancer bone metastasis by inhibiting CXCR4 and MMP-9 expression through downregulation of the NF-κB signaling pathway." (PMID 28698459, 2017).